LOX (lysyl oxidase)
Diseases named in the same sentence as LOX in open-access papers (continued):
Sharing a sentence is not in itself a finding about the gene and the disease.
tumor (continued). "The bioinformatics analysis showed that patients with high LOX levels had poor OS; low levels of methylation at some cg sites in the LOX gene were strongly related to poor OS and PFS; and methylation levels of LOX are negatively correlated with advanced tumor stage." (PMID 36202905, 2022). "proved that the overexpression of LOX activated the angiogenesis partially through increasing the VEGF and enhancing the tube formation ability of endothelial cells in tumor initiating cells (TICs)-enriched HCC, and LOX inhibitor β-aminopropionitrile (BAPN) reverses the angiogenesis." (PMID 35311155, 2022). "Several genes were recognised targets of those microRNAs, and at least two (LOX, VEGFA) were already known to be involved in GBM tumourigenesis: LOX, a cofactor of HIF-1 which helps tumour cell to adapt to hypoxia, and VEGFA, known to be upregulated in older GBMs." (PMID 35327445, 2022). "The immunofluorescent stains indicated that FR17 intervention successfully down-regulated the expression of LOX, FN and POSTN in the lung induced by tumor-derived factors to impede the construction of PMN, which probably resulted in the decrease in MDSC recruitment." (PMID 35614076, 2022). "Copper is also an essential cofactor of various metalloproteins known to be closely correlated with tumor growth and metastatic invasion (Mitogen-Activated Protein Kinase Kinase 1 (MAP2K1), lysyl oxidase (LOX) and lysyl oxidase-like, (LOXL), Secreted Protein Acidic and Cysteine Rich (SPARC)...)." (PMID 35456648, 2022). "The LOX family, with five paralogs: LOX and LOX-like 1–4 (LOXL 1–4), play a vital role in catalyzing the cross-linkage of collagen and elastin and thus are involved in the formation of primary tumor and the establishment of metastases." (PMID 34583752, 2021). "Moreover, the levels of tumor metastasis-related molecules, HIF-1α expression, and LOX secretion were increased in RT-R-MDA-MB-231 tumor tissue compared to MDA-MB-231 tumor tissue and were even higher in CD24−/low/CD44+ tumor tissue." (PMID 34502547, 2021). "In this study, we first investigated the mRNA expression of LOX between tumor and adjacent non-cancer tissues in multiple databases and further investigated the correlation of LOX with clinical characteristics of STAD." (PMID 35047494, 2021). "Since activated PBT are not specific to the tumor, the effects observed are due to LOX inhibition and not due to T cells engaging in stable conjugates with cancer cells through antigen recognition." (PMID 34106045, 2021). "Moreover, HIF-1α/LOX induction and ESM-1 expression, which are involved in tumor metastasis and progression, were enhanced in CD24−/low/CD44+ cells compared to TNBC and RT-R-TNBC cells." (PMID 34502547, 2021). "Impact of LOX inhibition on T cell migration in EGI-1, MMTV-PyMT, mPDAC, and KPC tumor models." (PMID 34106045, 2021). "Additionally, osteoclastogenesis can be driven by LOX independently of RANKL, leading to osteolytic lesions within the bone microenvironment that support the colonization of tumour cells and the formation of overt bone metastases." (PMID 35006432, 2021). "Effect of LOX inhibition on ECM architecture in EGI-1, KPC, MMTV-PyMT, and mPDAC tumor models." (PMID 34106045, 2021). "A significant amount of experimental evidence supports the notion that changes in LOX levels alter ECM mechanics and contribute to cancer progression, and several studies have demonstrated that LOX activity is closely correlated with tumor stiffness and the invasiveness of cancer." (PMID 34572752, 2021). "Similarly, the LOX pro-peptide inhibits Akt and ERK1/2 signaling in Ras transformed cancers and reduces tumour volume in vivo." (PMID 33513979, 2021). "Indeed, EGFL7 binds to all members of the LOX family including LOX and LOXL1–4, indicating its importance in the regulation of tumor ECM stiffness." (PMID 33804387, 2021).
tumor (continued). "To further investigate the effects of matrix stiffness on OC progression in vivo, we conducted an orthotopic OC xenograft and used β-aminopropionitrile (BAPN), a classical LOX inhibitor that was commonly used in interrogating mechanical properties of ECM, to decrease the tumor stiffness in vivo." (PMID 34538264, 2021). "In fact, during the early stage of metastasis in several tumours, hypoxia regulates PMN formation by inducing several members of LOX family, including LOX, LOX-like (LOXL) 2 and LOXL4, and by providing cytokines and growth factors recruiting CD11b+ Ly6CmedLy6G+ myeloid cells." (PMID 34943819, 2021). "Of note, defects in either LOX activity 88, or absence of sites of LOX crosslinking (e.g., collagen telopeptides) have been shown to play a role in tumor invasion and metastasis." (PMID 32042347, 2020). "Previous studies suggest that IRF-1 has an anti-tumor effect through growth inhibition and induction of apoptotic genes including caspase, tumor necrosis factor-related apoptosis-inducing ligand (TRAIL), and lysyl oxidase (LOX)." (PMID 32294904, 2020). "A potential explanation for this distinction is that the increased ATOX1 expression in ER-positive tumors influences mitogen-activated protein kinase (MAPK) signaling, perhaps via the ATOX1–ATP7A–lysyl oxidase (LOX) axis, which in turn promotes tumor growth and metastasis." (PMID 31898157, 2020). "Secondary signaling mechanisms due to peroxide generated during the catalytic reaction of LOX, including HIF-1α, and the involvement of LOX in various tumor types, have been reviewed extensively and are not discussed here." (PMID 32708046, 2020). "In addition, the forkhead box M1b (FoxM1b), a transcription factor which exerts a pro-tumor effect on HCC, has been reported to play a positive role in LOX and LOXL2 expression." (PMID 33371259, 2020). "Focusing on tumor samples, we did not observe a clear stratification according to the tumor histotype, even though high LOX and COL1A1 levels were detected in ATCs." (PMID 31906302, 2020). "In an in vitro 3D spheroid model using four different mouse tumor cell lines, including Lewis lung carcinoma cell line (LLC), a fibrosarcoma cell line (MT6) and two breast carcinoma cell lines (4T1, EMT6), LOX inhibition significantly improved the diffusion of doxorubicin." (PMID 31106200, 2019). "Tumor ECM is typically stiffer than normal tissue ECM due to overexpression of many ECM components (e.g., collagens I, II, III, V, IX, and XI, heparan sulfate proteoglycans) and ECM-modifying enzymes [e.g., lysyl oxidase (LOX)]." (PMID 31334229, 2019). "HIF-1α is a master regulator of the adaptive response to hypoxia that induces the transcription of genes such as vascular endothelial growth factor (VEGF), lysyl oxidase (LOX), GLUT1, and PDK1, which sustain vascularisation, metastasis, and tumour cell survival." (PMID 31052256, 2019). "High expression of LOX has recently been reported within high-grade serous ovarian cancer (HGSOC) omental metastases compared to benign human omentum, where it promotes collagen crosslinking and tumor cell invasion." (PMID 31130685, 2019). "For example, lysyl oxidase (LOX), a secreted collagen cross-linking enzyme, has been determined to have elevated expression in the premetastatic niche and is able to increase tumor cell colonization during the metastatic cascade." (PMID 31105883, 2019). "ECM remodeling enzymes such as LOX, LOX-like protein 2 (LOXL2), LOXL4, MMP2, MMP9 and MMP14 and growth factors inducing collagen deposition (e.g., VEGF) are HIF-regulated genes that are involved in tumor fibrosis." (PMID 31334229, 2019). "When the LOX inhibition group was compared with the control group, the enzyme activity of the active form of MMP-2 (62 kDa) in mouse tumor tissues was significantly decreased (P < 0.05) and the enzyme activity of the active form of MMP-9 (92 kDa) was significantly decreased (P < 0.05)." (PMID 31777578, 2019).
tumor (continued). "Several studies have shown that LOX and LOXL2 promote angiogenesis to drive tumor metastasis." (PMID 30704479, 2019). "EVs released into TME either by tumor cells or stromal cells were shown to induce tumor angiogenesis, ECM remodeling and metastasis, albeit through activating known pro-angiogenic signaling molecules such as HIF, MMP, PI3K/AKT and LOX." (PMID 31921855, 2019). "In contrast, none of the genes found in tumor fragments to be regulated by translation (LOX, WISP), abundance (FOXC1, COL5A2, ITGA11) or buffering (SNAI2) were modulated by mTORC1 in U87-MG cells." (PMID 31052505, 2019). "All these data together suggest that under physiological conditions pro-LOX, and not LOX-PP, is the main tumor suppressor in NIH3T3 cells." (PMID 30701028, 2018). "Inhibition of LOX activity by BAPN has been found to inhibit invasion and migration of tumor cells in vitro and to reduce metastasis formation in vivo, but no or only a marginal inhibition of cell proliferation by BAPN in standard 2D cultures has usually been observed." (PMID 30701028, 2018). "The results so far indicated that high lysyl oxidase activity by increasing ECM cross-linking and stabilizing collagen content deprives the tumor of necessary supply, which also delimits transport of drugs into the tumor." (PMID 29780168, 2018). "LOX showed strong staining in both KM and FM3A SiLN removal groups.CD11b+ BMDCs have a variety of functions which may enhance metastatic tumor growth." (PMID 29848296, 2018). "Among the LOX family, the function of LOXL1, LOXL3 and LOXL4 is poorly understood, while evidence shows that overexpression of LOX and LOXL2 may be involved in the multiple steps of tumor metastasis and contributes to cancer progression." (PMID 29472856, 2018). "Moreover, human tumor tissue microarray further confirmed the possible correlation between P-EGFR and LOX." (PMID 29472856, 2018). "The complex nature of LOX protein domain structure and biological functions makes noticeable that it can act as both a tumor suppressor and a metastasis promoter gene in cancer." (PMID 28143503, 2017). "On the other hand, before tumor arrival in the metastatic sites, the primary tumor also produces systemic factors, for example, VEGFA, TGFβ, TNF, and LOX, which induce chemotactic protein expressions like S100A8, S100A9, SAA3 and extracellular matrix remodeling." (PMID 29450136, 2017). "Finally, like BAPN or genetic ablation of LOX, CCT365623 downregulates MATN2 and inhibits EGFR plasma membrane localization in tumours, and it suppresses tumour growth and metastasis in mice." (PMID 28416796, 2017). "Although LOX has previously been linked to SRC8, its role in EGFR signalling has not been reported, but like LOX, EGFR is implicated in both tumour cell growth and metastasis." (PMID 28416796, 2017). "This suggests that CRC tumour cells, which already exhibit elevated LOX expression, do not upregulate LOX further in response to RT." (PMID 28947950, 2017). "Since RT had no influence on LOX expression in primary tumour; we combined non-RT and RT groups together for further analysis." (PMID 28947950, 2017). "Moreover in vivo inhibition of LOX by our inhibitor CCT365623 disrupts this signalling axis and reduces tumour progression." (PMID 28416796, 2017). "This demonstrates that the extracellular target for LOX was only present in the tumour stroma during early tumour stages in this model and almost absent within the tumour stroma at later time points." (PMID 26804196, 2016). "This shows that the main target for extracellular LOX activity in established tumours is probably not within but outside tumours." (PMID 26804196, 2016). "LOX expression was detected in glandular epithelial cells and in stromal smooth muscle cells in both tumour-adjacent non-malignant prostate tissue and tumour-free normal rat prostate tissue." (PMID 26804196, 2016).
tumor (continued). "As neither inhibition of LOX enzymatic activity with BAPN nor stimulation with recombinant LOX protein affected AT-1 viability in vitro, LOX does probably not directly affect tumour cell viability." (PMID 26804196, 2016). "It has been demonstrated that LOX is a metastasis promoting gene as it is important for tumor progression to metastasis but not for tumor formation." (PMID 26908052, 2016). "In the current study we did not consider the cooperative roles of tumor-derived LOX and Endo180 in driving the plasticity of tumor cell movement on human fibroblast-derived and osteoblast-derived ECM surfaces." (PMID 26567111, 2016). "Treatment with BAPN or stimulation with recombinant LOX peptide did not affect tumour cell viability in vitro, suggesting that LOX does not affect the AT-1 tumour cells directly." (PMID 26804196, 2016). "LOX did not affect AT-1 tumour cell viability at any of the concentrations or under any of the conditions used." (PMID 26804196, 2016). "The intensity of LOX immunoreactivity was, however, not significantly different in the tumour-adjacent prostate tissue and in tumour-free prostate tissue." (PMID 26804196, 2016). "Here we show that orthotopic implantation of rat prostate AT-1 tumour cells increased LOX and LOXLs mRNA expressions in the tumour and in the surrounding non-malignant prostate tissue." (PMID 26804196, 2016). "The effects of BAPN treatment on tumour growth seen in our animal model are therefore probably due to LOX activities in the tumour stroma and/or the surrounding tumour-adjacent non-malignant prostate stroma and epithelium." (PMID 26804196, 2016). "In radical prostatectomy specimens, LOX immune-staining corresponded to LOX in-situ hybridization and LOX mRNA levels were found to be similar between tumor and adjacent non-malignant areas, but significantly increased in bone metastases samples." (PMID 26501565, 2015). "Currently, numerous studies support that the tumor suppressor activity of LOX resides in the 18-kDa propeptide fragment LOX-PP and not in the lysyl oxidase enzyme." (PMID 26258070, 2015). "LOX expression has shown to be regulated by hypoxia and implantation of cancer cells induced hypoxia in the non-malignant parts of the tumor-bearing prostate lobe in rats." (PMID 26501565, 2015). "MMP-2, MMP-9, LOX, CXCR4, FN and p-FAK are involved in remodeling the tumor metastatic microenvironment, and whether miR-33b can regulate the metastatic microenvironment deserves further investigation." (PMID 25919570, 2015). "As we have previously observed, an absence of metastasis alone was not sufficient to increase survival in the LOX-treated mice as they still became sick of primary tumor burden." (PMID 26077591, 2015). "This suggests that in contrast to the potentially oncogenic role of total depletion of tumor myofibroblasts, blockade of collagen cross-linking and LOX should not have tumor-promoting effects." (PMID 26077591, 2015). "Hypoxic conditions were chosen because it has been shown that higher expression of LOX may correlate with a higher uptake of 18F-labeled fluoroazomycin arabinoside ([18F]FAZA), a PET radiotracer for imaging tumor hypoxia." (PMID 26265048, 2015). "LOX mRNA was mainly expressed in the luminal prostate epithelial cells and in tumor cells with few positive cells in the non-malignant and malignant prostate stroma, showing that LOX was mainly produced in prostate epithelial and tumor cells." (PMID 26501565, 2015). "Hypoxia could thus explain the increased LOX levels in TINT and that increased levels of LOX is a consequence of tumor formation." (PMID 26501565, 2015). "LOX score in tumor and non-malignant prostate stroma appeared unrelated to these tumor characteristics." (PMID 26501565, 2015). "There were no significant relations between patient survival and LOX IR in tumor epithelium, tumor stroma or TINT stroma (data not shown)." (PMID 26501565, 2015).
tumor (continued). "In these samples the transcript level of LOX mRNA was similar in non-malignant and malignant primary tumor tissue." (PMID 26501565, 2015). "Here we show that the LOX score in prostate TINT epithelium correlates with many factors previously examined in TINT epithelium (pEGFR, pAKT) and TINT stroma (microvessel density) and shown to relate to tumor aggressiveness and outcome." (PMID 26501565, 2015). "This suggested that although LOX inhibition can have an effect on the tumor cells in culture, this was not sufficient to affect tumor proliferation in vivo." (PMID 26077591, 2015). "Of note, we here did not observe an increase of murine LOX in the serum of mice not carrying tumor xenografts but still locoregionally irradiated (data not shown)." (PMID 25052686, 2014). "Within the tumor microenvironment, tumors release extracellular signals such as vascular endothelial growth factor (VEGF), matrix metalloproteinases (MMPs), lysyl oxidase (LOX), and nucleotides to survive." (PMID 25238333, 2014). "Conditioned media from irradiated tumor cells promoted invasiveness of naïve tumor cells, while conditioned media from irradiated, LOX- siRNA-silenced cells did not stimulate their invasive capacity." (PMID 25052686, 2014). "Tumor microenvironmental hypoxia induces hypoxia inducible factor-1α (HIF-1α) overexpression, leading to the release of lysyl oxidase (LOX), which crosslinks collagen at distant sites to facilitate environmental changes that allow cancer cells to easily metastasize." (PMID 25238333, 2014). "Locoregional irradiation of mice not carrying tumor xenografts did not result in increased LOX in the serum above basal level and mouse-LOX levels did not change (data not shown)." (PMID 25052686, 2014). "LOX mediated collagen cross-linking seems to function in synergy with MMPs, which may lead to ECM remodeling favoring tumor progression." (PMID 24338768, 2014). "Here, we present data that LOX is overexpressed in EOC tumor tissues compared with non-cancer tissues." (PMID 23545606, 2013). "The difference in LOX expression between tumor cells and adjacent noncancerous mucosa was significant (42.2 vs. 12.4%, P<0.05)." (PMID 23425977, 2013). "In these studies, LOX was considered to be important for late-stage tumor progression to metastasis, but not for earlier stages involving tumor formation." (PMID 23425977, 2013). "LOX and HIF-1 act in synergy to help tumor cells adapt to hypoxia." (PMID 23658659, 2013). "Ongoing studies on the interaction of LOX and DDR2 signaling in the tumor microenvironment may further explain the relationship between collagen dysregulation and cancer invasion and metastasis." (PMID 21288331, 2011). "Reduction of lysyl oxidase (LOX), a copper-dependent amine oxidase that catalyses the crosslinking of collagens, elastin, and fibrillin in the ECM reduces matrix stiffening and thereby impedes malignancy and affects tumor development in MaCa." (PMID 21914164, 2011). "In addition to microarray analysis, quantification of the tumor hypoxia regulated genes CA9 and LOX was performed with real time PCR." (PMID 21477371, 2011). "Although its role in GBM remains to be defined, the presence of LoX in a genomically stable tumor suggests it may represent a non-canonical route to dysregulation, independent of classical CIN pathways." (PMID 41282088, 2025). "CSCs themselves modify the tumor microenvironment to replicate the conditions of stem cell niches, promote epithelial-mesenchymal transition (EMT) in nearby tumor cells, and alter the microenvironment of distant tissues by secreting factors such as VEGFA, LOX, TGFβ, and TNFα to promote metastasis." (PMID 40813991, 2025). "Additionally, LOX enzymes may contribute to the maintenance of cancer stem cell properties by altering the ECM niche, thereby supporting tumor recurrence and resistance to therapy." (PMID 40661776, 2025).